ACTB (actin beta)
Diseases named in the same sentence as ACTB in open-access papers (continued):
Sharing a sentence is not in itself a finding about the gene and the disease.
melanoma (19 papers, 2016 to 2025). A malignant, usually aggressive tumor composed of atypical, neoplastic melanocytes. "Including, ACTB as a hub protein associated with tyrosinase-mediated melanogenesis in melanoma cells." (PMID 38754850, 2024). "Finally, ACTB is closely associated with a variety of cancers and accumulating evidence indicates that ACTB is de-regulated in liver, melanoma, renal, colorectal, gastric, pancreatic, esophageal, lung, breast, prostate, ovarian cancers, leukemia and lymphoma." (PMID 34753514, 2021). "The research results suggested that ACTB was involved in the formation of melanin in melanocyte or melanoma cells." (PMID 38754850, 2024). "We found that the crucial biotargets of Salvia miltiorrhiza against melanoma include ACTB, also known as β-actin." (PMID 38398656, 2024). "We observed an increased amount of ACTB gene mRNA in advanced melanoma patients, both at the onset of the disease and in patients experiencing disease progression after six months of therapy." (PMID 37511550, 2023). "Evidence increasingly demonstrated that ACTB is dysregulated in liver, melanoma, kidney, colorectal, gastric, pancreatic, esophageal, lung, breast, prostate, ovarian, leukemia and lymphoma." (PMID 33795012, 2021). "Based on our data, we recommend the use of a combined geometric mean of the expression levels of CLTA, MRPL19 and ACTB for normalization of gene expression in FFPE melanomas." (PMID 31567589, 2020). "We recommend using a geometric mean of the expression of CLTA, MRPL19 and ACTB for normalization of gene expression in melanomas and a geometric mean of the expression of CASC3 and RPS2 for normalization of gene expression in melanoma cell lines." (PMID 31567589, 2020). "Indeed, the association of ACTB with a wide range of cancer types (liver, renal, colorectal, gastric, pancreatic, esophageal, lung, breast, prostate, and ovarian cancers and leukemia, melanoma, and lymphoma) has been explained and that of ACTBL2 in some hepatocellular carcinoma has been reported." (PMID 28018022, 2016). "One housekeeping gene, ACTB, did have a significant difference in expression between the two groups (p-value 0.041), though this gene has been shown to be upregulated in a variety of cancers, including melanoma." (PMID 36230844, 2022). "However, the ACTB gene was found to be differentially expressed in many different types of cancer such as liver, melanoma, renal, colorectal, gastric, pancreatic, esophageal, lung, breast, prostate, ovarian cancers, leukemia, and lymphoma under certain conditions." (PMID 38397141, 2024). "We investigated the expression stability of ACTB and GAPDH across four melanoma cell lines; FM3, FM82, FM88 and FM92." (PMID 31567589, 2020). "It should also be noted that in general the average expression of ACTB and GAPDH the skin samples is fairly low compared to their expression in the melanoma samples." (PMID 31567589, 2020). "We identified CLTA as the most robust reference gene for normalization of gene expression in primary melanomas followed by MRPL19 and ACTB, respectively." (PMID 31567589, 2020). "In this study, we have analyzed the intra- and inter-tumor expression stability of the two commonly used reference genes, ACTB and GAPDH, in 13 FFPE melanoma samples by qRT-PCR." (PMID 31567589, 2020). "The distribution of PTCH1 gene expression level for all TCGA patients compared to genes known to be well expressed in melanoma (GAPDH, ACTB, MITF) indicates that PTCH1 is well expressed in primary and metastatic samples." (PMID 32526884, 2020). "We further compared the relative gene expression ratios of target genes LRP1, ACTB and GAPDH across 13 melanoma cell lines estimated by qRT-PCR or ddPCR." (PMID 31567589, 2020). "Upon normalization of the results to A375 cells there were statistically significant differences in ACTB and ACTG1 expression for other melanoma cells lines when compared to A375 cells, however the differences were not so high varying form ca. 0.5- to 2-fold." (PMID 32326615, 2020).
melanoma (continued). "Furthermore, results of GEPIA analysis showed that ACTB, SLC1A5, VASP, BRBB3, GAS7, ARTN2, and SOX5 were significantly increased in melanoma tissues (p < 0.05)." (PMID 38561355, 2024). "Next, we checked the expression levels of ACTBL2, ACTB, and ACTG1 in five melanoma cell lines." (PMID 33558623, 2021). "The expression of ACTB and GAPDH in 13 primary melanomas was investigated by qRT-PCR." (PMID 31567589, 2020). "By comparing the relative expression ratios of target genes LRP1, ACTB and GAPDH across two melanoma cell lines estimated using an RNAseq approach and a qRT-PCR-based approach, we show that indeed we obtain similar relative gene expression levels of the target genes." (PMID 31567589, 2020). "Even though we macrodissected all skin and melanoma sections before RNA extraction and only included RNA samples with comparable RIN values, we observed a large degree of variation in gene expression levels of ACTB and GAPDH across the 13 melanoma samples investigated." (PMID 31567589, 2020). "Multiple sections of each tumor were analyzed (minimum n = 3; maximum n = 6 per tumor), and inter- and intra-tumor variation in gene expression was evaluated to assess if ACTB and GAPDH could qualify as reference genes in qRT-PCR-based analysis of gene expression in melanoma tissue samples." (PMID 31567589, 2020). "We also examined the expression of ACTB and GAPDH in non-cancerous epidermal tissue samples taken from the melanoma patients, and we found that the expression of ATCB and GAPDH vary substantially between the normal epidermal tissue samples as well." (PMID 31567589, 2020). "mSEPT9 was not detectable in 125 μL of melanoma RPMI-7951 SFCM, although ACTB was present." (PMID 35992328, 2022).
Baraitser-Winter syndrome (15 papers, 2013 to 2025). "Baraitser-Winter syndrome (BRWS) is a rare genetic disorder caused by mutations in the ACTB and ACTG1 genes." (PMID 38361693, 2024). "Lymphocytes from a patient carrying an ACTB E117K mutation seen in an atypical form of Baraitser-Winter syndrome, show decreased ability to adhere to fibronectin surfaces and show less protrusive structures." (PMID 32349449, 2020). "Further, missense mutations in either ACTB or ACTG1 have recently been reported to cause Baraitser-Winter syndrome." (PMID 23506231, 2013). "To investigate the pathogenesis underlying this cortical malformation, we studied patient-derived cerebral organoids from induced pluripotent stem cells of individuals with the Baraitser-Winter-CerebroFrontoFacial syndrome (BWCFF-S) carrying an ACTB/ACTG1 missense mutation." (PMID 41372632, 2025). "Studies displayed that mutations in ACTB can cause Baraitser-Winter syndrome." (PMID 36691005, 2023). "Studies have found that missense mutations of ACTB may cause Baraitser-Winter syndrome (BRWS) in humans, characterized by intellectual disability, cortical malformations, coloboma, organ malformation." (PMID 32970714, 2020). "ACTB encodes the β-actin, and pathogenic variations in this gene have typically been associated with Baraitser-Winter cerebrofrontofacial syndrome, a congenital malformation syndrome characterized by short stature, craniofacial anomalies, and cerebral anomalies." (PMID 28487785, 2017). "Baraitser-Winter Syndrome (B-WS, OMIM #243310, #614583) is a rare, multiple-anomaly genetic disorder caused by mutations in either cytoplasmically expressed actin gene, ACTB (β-actin) or ACTG1 (γ-actin)." (PMID 35054877, 2022). "Germline mutations in the ubiquitously expressed ACTB, which encodes β-cytoplasmic actin (CYA), are almost exclusively associated with Baraitser-Winter Cerebrofrontofacial syndrome (BWCFF)." (PMID 30315159, 2018). "Genetic variants in ACTB and ACTG1 have been associated with Baraitser-Winter Cerebrofrontofacial syndrome." (PMID 30315159, 2018). "Likewise, individuals with ACTB and ACTG1 variants and Baraitser-Winter syndrome frequently present with neuronal migration disorders like lissencephaly and pachygyria resulting in mild intellectual disability and seizures." (PMID 34805998, 2021).
prostate carcinoma (13 papers, 2007 to 2021). A carcinoma that arises from epithelial cells of the prostate gland. "Contradictory findings also exist, with ACTB observed to be stably expressed in some breast and prostate cancer cell lines under hypoxic conditions." (PMID 34035373, 2021). "Considering prostate cancer cell types, ACTB/GAPDH and ACTB/HPRT1 are the most suitable reference gene combinations for mRNA analysis, and miR-16/miR-1228-3p and RNU6-2/RNU43 for miRNA analysis in AR+, and AR− and normal cell lines, respectively." (PMID 29386530, 2018). "Considering prostate cancer cell types, ACTB /GAPDH and ACTB/HPRT1 are suggested to be the most suitable reference gene combinations for mRNA analysis." (PMID 29386530, 2018). "Furthermore, in prostate cancer, ACTB, RPL13A and HMBS showed significant differences between cancer and noncancerous tissues." (PMID 17640361, 2007). "For instance, ACTB has been considered a stable control gene in breast (MCF-7 cell line) and prostate cancer (LNCaP, 22Rv1, PC3, and DU14) cell lines under hypoxia." (PMID 27835695, 2016). "A particularly striking example in this regard, is the contrast between our results and the reported in prostate cancer tissue, where HPRT1 was the most stable gene, and RPL13A and ACTB were the most unstable." (PMID 18226276, 2008). "For example, percentages of alterations in CAP2, CAP1, CFL1, CFL2, DSTN, ACTB, and ACTG1 genes among prostate cancer varied from 2.6–30% in individual genes (CAP2, 19%; CAP1, 13%; CFL1, 30%; CFL2, 21%; DSTN, 19%; ACTG1, 2.6%; ACTB, 21%;); the CFL1 gene was amplified predominantly in prostate cancer." (PMID 28423713, 2017). "A previous study has shown significantly different expressions of ACTB between malignant and non-malignant pairs, upon examination of 16 potential reference gene candidates in 17 untreated prostate carcinomas." (PMID 29180379, 2017). "Hence, we also used β-actin (ACTB) which was not significantly altered in bladder cancer or prostate cancer." (PMID 26468005, 2015).
lung carcinoma (12 papers, 2008 to 2024). "We analyzed the pathological staining of proteins in tumor patients using the HPA database and observed that ACTB exhibits strong positivity (>75%) in glioma, head and neck cancer, liver cancer, and lung cancer and moderate positivity (75–25%) in renal cancer." (PMID 39329952, 2024). "The qPCR reactions were performed on the 196 collected lung cancer samples and the detection was successful for 170 samples based on the successful amplification of ACTB internal control in both qPCR reactions for each sample." (PMID 31369639, 2019). "By contrast, as in the lung cancer cell lines, ACTB showed the least stable expression." (PMID 37501994, 2023). "Although the cell lines have different properties, in statin-treated lung cancer cells, RPLP2 expression was stable, whereas ACTB appeared to be an unstable internal reference gene." (PMID 37501994, 2023). "PMR values >100% have been previously reported for SHOX2 in lung cancer, when ACTB was used as a reference, and were attributed to amplification of the SHOX2 locus or deletion of the ACTB locus." (PMID 27999621, 2016).
Intellectual disability (11 papers, 2017 to 2023). "Loss-of-function of the ACTB gene in humans is associated with developmental delays or intellectual disability." (PMID 31375980, 2019). "Common features amongst this cohort of patients with 3′ ACTB variants include developmental delay, mild intellectual disability, microcephaly, and thrombocytopenia with platelet anisotropy and enlarged platelets." (PMID 30315159, 2018). "In conclusion, we show that heterozygous loss-of-function ACTB mutations cause a distinct pleiotropic malformation syndrome with intellectual disability." (PMID 29220674, 2017). "After consolidating intellectual disability gene lists from two databases and one recent review article, we identified eight LRRK2 interacting proteins that have previously been linked to intellectual disability: ACTB, ACTG1, ATRX, DYNC1H1, HERC2, PPP2R1A, TUBA1A, and YWHAE." (PMID 31963867, 2020).
leukemia (11 papers, 2013 to 2025). A malignant (clonal) hematologic disorder, involving hematopoietic stem cells and characterized by the presence of primitive or atypical myeloid or lymphoid cells in the bone marrow and the blood. "Compared with that in the normal tissues, the expression of ACTB is increased in head and neck cancer, leukemia, pancreatic cancer, and other cancers." (PMID 38649690, 2024). "qRT-PCR was performed for each of the 14 new genes, as well as for 5 standard control genes (GAPDH, ACTB, TBP, HPRT1, ABL1), on cDNA from a panel of 14 leukemia samples (10 AML, 4 ALL) plus one CD34+ cord blood sample (using equal amounts of RNA)." (PMID 24069164, 2013).
COVID-19 (10 papers, 2021 to 2025). A disease caused by infection with severe acute respiratory syndrome coronavirus 2. "We screened for statistically significant hub genes and found that ACTB was in low expression of both BD and COVID-19, and ASPM, CCNA2, CCNB1, and CENPE were in low expression of BD and high expression of COVID-19." (PMID 37335738, 2023). "From the results, it can be seen that the expression levels of hub genes were elevated in the COVID-19 samples compared with the normal group, except for ACTB." (PMID 37335738, 2023). "Meanwhile, SARS-CoV-2 host genes, such as ACTB, KPNA2, and JUN, interact with SAMHD1, VCAM1, and HMOX1, in the PPI network, indicating possible mechanisms of COVID-19 associated stroke." (PMID 33732102, 2021). "Understanding the role of ACTB in these processes could provide insights into managing COVID-19–related inflammation." (PMID 40919176, 2025). "Furthermore, the roles of other stroke-associated genes, such as SAMHD-1, DDAH-1, HMOX1, LTC4S, ACTB, KPNA2, and JUN, in mediating stroke secondary to SARS-CoV-2 infection are required to be further explored experimental using COVID-19 patient samples or SARS-CoV-2 animal models." (PMID 33732102, 2021). "In the coagulation pathway, we found that IVIG treatment decreases KNG1 and ACTB and increased FGA relative to COVID-19 controls, although the variance in FGA levels was similar between groups." (PMID 40821834, 2025). "Specifically, we found a set of 89 DE genes in COVID-19 macrophages from all three organs, including PLCG2, HIF1A, ACTB, and JUND." (PMID 37830426, 2023).
glioma (10 papers, 2009 to 2024). A benign or malignant brain and spinal cord tumor that arises from glial cells (astrocytes, oligodendrocytes, ependymal cells). "In the next part of the study, changes in the expression levels of TGFβ1, TGFβ2, TGFβ3, and ACTB were evaluated in gliomas with different degrees of malignancy." (PMID 35454784, 2022). "Cox proportional hazards regression analysis was then carried out using both log-scaled ratios of EFEMP1 and EGFR vs ACTB (continuous variables) and dichotomized variables for these 166 gliomas." (PMID 25594013, 2014). "Three TGFβ isoforms and ACTB were detected in all 43 glioma samples." (PMID 35454784, 2022). "Note a significant TREM1 enhancement in high-grade WHO IV gliomas compared to low grades WHO I–II and grade III gliomas; TREM1 expression was normalized to the corresponding ACTB expression in each analyzed sample." (PMID 36249290, 2022). "Bioinformatic analysis of genes of interest against TCGA RNA sequencing data proposed TRIM28, VIM, NAP1L1 and DPYSL2 as promising “glioma versus reference” biomarkers, and suggested CRMP1, NAP1L1, NUCL, ACTB and VIM for discrimination between GBM and LGG." (PMID 28498803, 2017). "We demonstrate the potential use of NAP1L1, NUCL, CRMP1, ACTB, and VIM for differentiation between glioblastoma and lower grade gliomas, with DPYSL2 as a promising “glioma versus reference” biomarker." (PMID 28498803, 2017). "In 166 glioma cDNA samples from that study, (95 GBMs, 36 AAs, and 35 OTs), we quantified EFEMP1 and obtained the absolute ratio of EFEMP1 to ACTB, using same-standard-based, real-time qRT-PCR." (PMID 25594013, 2014). "According to articles published over the past two years, three of them, ACTB, GAPDH and 18S rRNA, collectively correspond to the endogenous controls applied in more than 80% of expression analyses performed on glioma tumors or cell lines." (PMID 19257903, 2009). "In our opinion ACTB does not represent the best reference gene for normalization because it is located at 7p15-p12, a chromosomal site subject to copy number variations in gliomas, and because it is close EGFR (located at 7p12) that is amplified in about 40% of GBMs." (PMID 20167086, 2010).